NOTCH1 (notch receptor 1)
Diseases named in the same sentence as NOTCH1 in open-access papers (continued):
Sharing a sentence is not in itself a finding about the gene and the disease.
asthma (13 papers, 2010 to 2025). "Herein, we aimed to determine the effect of vitamin D (Vit D) and underlying mechanisms on asthma‐induced lung injury via regulation of HIF‐1α/Notch1 (hypoxia‐inducible factor 1 alpha/neurogenic locus notch homolog protein 1) signaling during autophagy." (PMID 35959262, 2022). "miR-139-5p has a potential protective role in inhibiting PM2.5-induced asthma airway inflammation by targeting Notch1." (PMID 39997934, 2025). "Given the HIF‐1α/Notch1 agonistic activity, Vit D treatment inhibited apoptosis cell numbers, which were increased following asthma‐induced upregulation of autophagy." (PMID 35959262, 2022). "Vitamin D improved asthma‐induced lung tissue injury by suppressing autophagy via regulation of HIF‐1α/Notch1 signaling in vivo." (PMID 35959262, 2022). "Vitamin D improved asthma‐induced lung tissue injury by suppressing autophagy via regulation of HIF‐1α/Notch1 (hypoxia‐inducible factor 1 alpha/neurogenic locus notch homolog protein 1) signaling in vivo." (PMID 35959262, 2022). "Activation of the Notch gene is crucial for Th2 response in asthma, and Notch 1 dysregulated signaling of T cells is observed through the hyperacetylation of H3K9, H3K14, H3K18, H3K27, and H3K16 and trimethylation of H3K4 and H3K79." (PMID 34566492, 2021). "In the OVA‐induced asthma mice model, Notch1, Notch2 and Notch3 were all highly expressed in the lung tissues." (PMID 32935466, 2020). "In this study, we demonstrated in vivo that Notch1 and Notch2 were indeed playing a positive role in asthma, but the effect of Notch2 was much lower than Notch1." (PMID 24706026, 2014). "Our findings showed that the levels of Notch1 and Notch2 receptors were up-regulated in asthma group, accompanied by the increased expression of GATA3." (PMID 24706026, 2014). "The expression of Notch1 and 3 was detected in the lung tissue of asthma model mice and they demonstrated reverse changes." (PMID 23420695, 2013). "Of note, Notch1, Notch2 and Notch3 are strongly overexpressed in the lung tissues of rats with ovalbumin‐induced asthma, and Notch1 inhibition by emodin treatment confers more remarkable transformations within the lung tissue than does Notch2 and Notch3 inhibition." (PMID 35355403, 2022). "Since Th2 cells are the most important inflammatory mediators of allergic asthma, we speculate that Notch1 and Notch2 receptor will be increased in asthma group." (PMID 24706026, 2014). "Guo and colleges have found that the level of Notch1 was significantly higher in asthma mice and Notch1 signal may play an important role in the pathogenesis of asthma by its involvement in Th1/Th2 differentiation." (PMID 24706026, 2014). "We also found that in curcumin pretreatment groups, the levels of Notch1 and Notch2 receptors were significantly decreased compared to asthma groups though still higher than normal mice, which suggested that curcumin might attenuate allergic airway inflammation through inhibiting Notch signaling." (PMID 24706026, 2014). "Research findings using rat models of asthma demonstrated that the presence of Notch1 and Notch2 on CD4+ T cells, along with Jagged1 on dendritic cells and/or Dll1 on smooth muscle cells, facilitated asthma development." (PMID 39450276, 2024). "Additionally, a study in China showed that in rodent asthma models, TGF‐β1/SMAD and Jagged1/Notch1 signaling pathways are regulated by recombinant pyrin domain protein to suppress asthmatic airway inflammation and airway remodeling." (PMID 36799806, 2023). "NOTCH1 is involved in the promotion of the GATA3-mediated Th2 response (immunity), which makes NOTCH1 an unlikely candidate responsible for the non-Th2 inflammatory pattern in asthma." (PMID 33980319, 2021). "In a mouse model of asthma, siRNA-mediated Notch1 blockade decreased IL-4 and increased IFN-γ in activated lung T cells, suggesting that Notch1 could play a role in regulating the Th1/Th2 imbalance." (PMID 33912195, 2021).
asthma (continued). "Suppression of Notch1 expression by HAT inhibitors reduced Th2 cytokines, especially IL-4, IL-5, and IL-13, and it may provide a therapeutic alternative for asthma." (PMID 34566492, 2021).
Hyperglycemia (13 papers, 2017 to 2025). An increased concentration of glucose in the blood. "The reduction of NO induced by hyperglycemia leads to an upregulation of Jarid2, an epigenetic repressor of Notch1." (PMID 37571325, 2023). "Intermittent hyperglycemia-challenged EC exhibited Notch activation as detected through an increase in Notch1-intracellular domain (N1-ICD) level and heightened expression level of Notch downstream target gene Hes1." (PMID 35392173, 2022). "To provide evidence that such changes also occur at the tissue level, we detected active Notch1 product N1-ICD and its associated ligands Jagged1 and Jagged2 in rat aorta tissues that were challenged with intermittent hyperglycemia ex vivo." (PMID 35392173, 2022). "Indeed, hyperglycemia is the principal cause of induced oxidative stress; therefore, exposing ECs to high glucose led not only to oxidative stress but also to upregulation in miR-200c, which subsequently induced EC apoptosis and senescence via Notch1 inhibition." (PMID 36555301, 2022). "Hyperglycemia can increase the expression of Notch1 protein and its downstream molecules involved in the pathogenesis of endothelial cell injury." (PMID 29464183, 2017). "Furthermore, MDM2-mediated activation of Notch1 has been identified as a mechanism contributing to hyperglycemia-induced proliferation of glomerular mesangial cells and the accumulation of extracellular matrix (ECM)." (PMID 41203613, 2025). "Thus, getting a better understanding of Notch1 signaling regulation during hyperglycemia is of great importance." (PMID 28871126, 2017). "For instance, hyperglycemia and hyperphosphatemia trigger the activation of Notch1-RBP-Jk/Msx2 pathway in DN to varying degrees and at different time periods, whereas the compensatory mechanism of the body may restore their levels." (PMID 29464183, 2017). "In addition, chronic hyperglycemia leads to upregulation of DII4, activating both canonical and rapid non-canonical Notch1 pathways." (PMID 34256844, 2021).
thyroid cancer (13 papers, 2015 to 2022). "Although PTC is the most common subtype of thyroid carcinoma, studies on the association between Notch1 signaling and its clinicopathological factors are limited." (PMID 30622441, 2019). "Furthermore, NOTCH1 pathway activation has been associated with the increase of P21 in thyroid cancer models." (PMID 34502288, 2021). "The results showed that there is a positive correlation between Nrf2 and Notch1 in thyroid cancers (r = 0.58, P < 0.05)." (PMID 34527171, 2021). "The expression levels of Notch-1 were downregulated in thyroid cancer tissues compared with thyroid tissues of benign." (PMID 33669363, 2021). "There are studies demonstrating that Notch-1 overexpression in thyroid cancer cells restores differentiation, stimulates the expression of differentiation markers, and reduces cell growth." (PMID 33669363, 2021). "Overexpression of the Notch signaling pathway, including that of Notch1, Notch3, and Hes1, is directly associated with a differentiation phenotype (NIS, TPO) expression of both thyroid cancers and TSH-stimulated normal thyroid cells." (PMID 33995657, 2021). "We also investigated the functional relationship of these TFs with NOTCH1 in the regulation of thyroid cancer biology." (PMID 30158530, 2018). "To further consolidate these observations, we analyzed the possible correlation between DEC1 and NOTCH1 expression in human thyroid cancer samples." (PMID 30158530, 2018). "First, we evaluated the mRNA expression profile of four members of the NOTCH family (NOTCH1–4) in thyroid cancer cell lines." (PMID 30158530, 2018). "We confirmed this observation in vivo showing that DEC1 expression is a specific feature of tumor cells, that this transcription factor is significantly over-expressed in all major thyroid cancer histotypes and that its expression correlated with NOTCH1 in these tumors." (PMID 30158530, 2018). "VEGF-A could play a more important role in the progression of thyroid carcinoma through angiogenesis process than Notch1 or Bcl-2." (PMID 30544959, 2018). "However, overexpression of NOTCH1 in thyroid cancer cells can induce differentiation and stimulate NIS expression." (PMID 27342319, 2016). "In thyroid cancers, the role of Notch1 signaling is tumor histological differentiation dependent." (PMID 25887589, 2015). "This study demonstrated the different roles of Notch-1 expression in cancer cell aggressiveness between ATC and PTC, suggesting the heterogeneity of CSCs in thyroid cancer." (PMID 33669363, 2021). "We demonstrated that DEC1 controls NOTCH1 expression and that the interplay with the NOTCH pathway is relevant for DEC1 function in thyroid cancer." (PMID 30158530, 2018). "Noticeably, over 60% (11 out of 18) of analyzed target genes were also coherently affected by NOTCH1 silencing, suggesting that these genes are also NOTCH1 targets and further supporting the functional interplay between DEC1 and NOTCH1 in thyroid cancer." (PMID 30158530, 2018). "Restoration of Notch-1 function reduced cell growth and migration in a doxycycline-inducible metastatic DTC cell line, as well as significantly reduced the primary tumor growth and inhibited the lung metastasis development in a thyroid cancer model." (PMID 33669363, 2021). "Moreover, knockdown of CNTN1 significantly repressed the expression of cyclin D1 (CCND1), a target gene of the Notch1 pathway, indicating CNTN1 to potentially regulate the expression of CCND1 by activating Notch1 in thyroid cancer." (PMID 33194679, 2020). "Finally, here we showed that DEC1 controls the expression of NOTCH1 and consequently the activation of the NOTCH pathway in thyroid cancer." (PMID 30158530, 2018). "Also, in thyroid cancer, NOTCH1 plays a controversial and not fully defined role." (PMID 30158530, 2018).
tongue cancer (13 papers, 2013 to 2025). A malignant neoplasm affecting the tongue. "There are several reports illustrating that NOTCH1 expression (mRNA and protein levels) is elevated in tongue cancer tissues, and NOTCH1 expression was associated with tumour stage and de-differentiation, or therapy resistance." (PMID 34944837, 2021). "The activation of Notch1 has been reported to cause cell cycle arrest in human tongue cancer cell lines." (PMID 24403239, 2013). "Furthermore, in a tongue cancer model using mouse xenografts, the presence of NOTCH1 caused a dramatic reduction in tumor size compared with tumors in which this gene was absent." (PMID 26395002, 2015). "Consistent with our findings, Notch1 expression was upregulated in tongue cancer tissues, and inhibition of Notch1 reduced proliferation, invasion, and migration of tongue cancer cells." (PMID 38866828, 2024). "provides more direct evidence of the tumor-regulating property of Notch1, which plays an important role in cell proliferation, apoptosis and invasion of tongue cancer cells." (PMID 36818671, 2022). "Some recent studies showed that overexpression of NOTCH1 can increase proliferation, invasion and migration of tongue cancer cells, and inhibition of NOTCH1 expression reverses these processes and instead promotes apoptosis in vitro and in vivo." (PMID 34944837, 2021). "In the case of tongue cancer, an increase in the expression of mRNA NOTCH1 was observed, whereas our analysis indicated the opposite result." (PMID 33917330, 2021). "In human tongue carcinoma the expression of NOTCH1 and NOTCH3 showed strong correlations with the clinical stage of the tumor." (PMID 32796631, 2020). "Notably, in human tongue cancer, Notch1 exhibited elevated expression and promotes TSCC invasion and metastasis by modulating the expression of matrix metalloproteinases (MMPs) and epithelial-mesenchymal transition." (PMID 38866828, 2024). "Several studies have indicated that the Notch-1 pathway could promote cell proliferation and inhibit apoptosis in human pancreatic, gastric, and tongue cancer." (PMID 35982489, 2022). "Furthermore, Notch1 expression was related to lymph node metastasis and the depth of cancer cell invasion in patients suffering from tongue cancer." (PMID 32796631, 2020). "We anticipate that these results could form the basis for therapeutic targeting of NOTCH1 in tongue cancer." (PMID 27391340, 2016). "Likewise, in tongue cancers, NOTCH1 activation has been shown to lead to promotion of EMT." (PMID 34944837, 2021). "LncRNA UCA-1 expression is induced upon TGF-β treatment in tongue cancer cells, and it promotes EMT and invasion by sponging miR-124 to promote JAG1/Notch1 signaling." (PMID 40594481, 2025). "Last not least, co-staining of NOTCH1 and vascular endothelial growth factor (VEGF) in tongue cancer tissues by immunohistochemistry (IHC) showed a positive correlation between expression of these molecules, stemness, and cancer invasiveness." (PMID 34944837, 2021).
B-cell lymphoma (12 papers, 2011 to 2024). "With regards to other haematologic malignancies, de-regulated NOTCH signalling was also discovered in B-cell lymphomas via mutations in the NOTCH1 and NOTCH2 genes." (PMID 36313682, 2022). "Similarly, NOTCH1 and NOTCH2 mutations are found in different B cell lymphomas, with NOTCH1 being recurrently mutated in chronic lymphocytic leukaemia (CLL) and NOTCH2 in marginal zone lymphoma." (PMID 31690218, 2019). "Remarkably, some of these genes (KLF2, TNFAIP3, NOTCH1, HIST1H2BE) are recurrently mutated in HBsAgpos DLBCL and in HCV-associated B-cell NHL." (PMID 39055707, 2024). "NOTCH1 represents an interesting candidate because it plays an essential role in mature B-cell malignancies such as chronic lymphoblastic leukemia or B-cell lymphoma and in T-ALL." (PMID 37422628, 2023). "The role of NOTCH1 in aberrant 3D chromatin reorganization has been also reported in B cell lymphoma, where NOTCH1 mediates spatial clusters of long-range E-P interactions forming hyperconnected “3D cliques”, which include crucial protooncogenes." (PMID 34054841, 2021). "This new insight provides impetus to better personalize the choice of rituximab or obinutuzumab for anti-CD20 treatment, to optimize the design of protocols encompassing anti-CD20 monoclonal antibodies, and to develop new strategies for the treatment of NOTCH1-driven B cell lymphoma." (PMID 33615197, 2021). "In this way, we detected the induction of transcription factors genes implicated in B-cell differentiation and activation, PAX5 and IRF8 as well as of MYBL2, a transcription factor participating in cell cycle progression and recently described as a direct Notch1 target in B cell lymphomas." (PMID 31676012, 2019). "This minireview focuses on recent advances related to the mechanisms and roles of activated Notch1, Notch2, Notch3 and Notch4 signaling in human lymphocytic leukemia, myeloid leukemia and B cell lymphoma, as well as their significance, and recent advances in Notch-targeted therapies." (PMID 22128846, 2011). "In B-cell lymphoma, NOTCH1 mutations are almost always located in exon 34 and affect the protein’s PEST-domain responsible for inactivation and degradation of the NOTCH1 intracellular domain (NICD1), which is released as transcription factor after NOTCH1 activation." (PMID 36313682, 2022). "NOTCH1, a member of the PCG gene family, was first discovered in mouse B-cell lymphoma and is regarded as a co-oncogene of C-MYC, closely related to cell proliferation, differentiation and apoptosis." (PMID 34136379, 2021).
Insulin resistance (12 papers, 2013 to 2024). Increased resistance towards insulin, that is, diminished effectiveness of insulin in reducing blood glucose levels. "Our study demonstrated that haploinsufficiency of Notch1 promotes fat accumulation and adipogenesis, and provides a mechanistic link between Notch signaling and development of insulin resistance." (PMID 34408185, 2021). "Notch1 was suppressed via curcumin treatment, which in turn ameliorated fatty liver and insulin resistance." (PMID 31805951, 2019). "In this study, Notch1 was up-regulated while FoxO pathway was over-represented, Notch1 could up-regulate FoXO1 which aggravated insulin resistance of NAFLD." (PMID 31805951, 2019). "Also, MMP9, ELANE, NOTCH1, with fewer connected targets, have all been proven to have important regulatory effects in reducing liver lipid accumulation, inflammatory responses, fibrosis, and improving insulin resistance." (PMID 36451177, 2022). "NOTCH1 and STAT5 have also been reported to be involved in amino acid metabolism to prevent insulin resistance, which contributes to DM progression." (PMID 37522815, 2023). "Insulin signaling inhibits ZFYVE28 expression by inhibiting NOTCH1 via the RAS/ERK pathway, whereas ZFYVE28 expression is elevated due to impaired insulin signaling in insulin resistance." (PMID 37884540, 2023). "Notch homolog 1 (NOTCH1) and NOTCH4 are components of the Notch signaling pathway, and activation of the Notch signaling pathway is important for the improvement of insulin resistance." (PMID 30678306, 2019).